TNFAIP2 (TNF alpha induced protein 2)
Diseases named in the same sentence as TNFAIP2 in open-access papers (continued):
Sharing a sentence is not in itself a finding about the gene and the disease.
triple-negative breast carcinoma (5 papers, 2023 to 2025). An invasive breast carcinoma which is negative for expression of estrogen receptor (ER), progesterone receptor (PR), and human epidermal growth factor receptor 2 (HER2). "KLF5 is highly expressed in triple-negative breast cancer and promotes cell proliferation, stemness, migration, and metastasis by regulating downstream target genes such as TNFAIP2 and XPO1." (PMID 40969325, 2025). "We previously reported that TNFAIP2 activates Rac1 to promote triple-negative breast cancer (TNBC) cell proliferation, migration, and chemoresistance." (PMID 39532855, 2024). "For instance, ITGB4 promotes triple-negative breast cancer to resist DNA damage via TNFAIP2/IQGAP1/RAC1, and thus accelerates the drug resistance of tumor cells." (PMID 38831335, 2024). "IQGAP1 mediates RAC1 activation by TNFAIP2 and promotes triple-negative breast cancer (TNBC) drug resistance." (PMID 37787041, 2023). "ITGB4 interacts with TNFAIP2 and promotes triple-negative breast cancer (TNBC) drug resistance and DNA damage repair." (PMID 37787041, 2023). "TNFAIP2 promotes triple-negative breast cancer (TNBC) drug resistance and DNA damage repair via RAC1." (PMID 37787041, 2023). "TNFAIP2 promotes triple-negative breast cancer (TNBC) DNA damage-related drug resistance." (PMID 37787041, 2023). "TNFAIP2 confers triple-negative breast cancer (TNBC) drug resistance in vivo." (PMID 37787041, 2023). "ITGB4 promotes triple-negative breast cancer (TNBC) drug resistance via TNFAIP2/IQGAP1/RAC1." (PMID 37787041, 2023).
acute promyelocytic leukemia (4 papers, 2021 to 2023). An aggressive form of acute myeloid leukemia (AML), characterized by arrest of leukocyte differentiation at the promyelocyte stage, due to a specific chromosomal translocation t(15;17) in myeloid cells. "The TNFAIP2 gene may be the target gene of retinoic acid in acute promyelocytic leukemia, and melanocytes are important target cells of retinoic acid." (PMID 36140707, 2022).
lung carcinoma (3 papers, 2015 to 2026). "Another mouse, with lung neoplasia, had 50% of its outliers within two genes, Lrba and Tnfaip2, both of which are linked to lung cancer." (PMID 41432313, 2026). "Biological information software (Targetscan, miRwalk, miRanda) have predicted that TNFAIP2 was one of the miR-184 target genes and have characterized TNFAIP2 as a direct target of miR-184 by a dual-luciferase reporter assay in lung cancer cells." (PMID 25888093, 2015).
myeloma (3 papers, 2018 to 2023). "Cell lines from lymphatic system (e.g., lymphoma and myeloma) expressed relatively less TNFAIP while intermediate expression level of TNFAIP2 was observed in AML cell lines." (PMID 36243694, 2022). "Interestingly, it has been shown that in myeloma cells, TNFAIP2 was significantly induced by cell adhesion to fibronectin, an extracellular matrix protein that is strongly overexpressed in GBM." (PMID 37511403, 2023).
skin cutaneous melanoma (3 papers, 2022 to 2024). "However, it has been reported that elevated levels of TNFAIP2 are strongly correlated with prolonged survival in multiple malignancies, including bladder urothelial carcinoma, sarcoma and skin cutaneous melanoma." (PMID 38271140, 2024).
cervical cancer (2 papers, 2020 to 2023). A primary or metastatic malignant neoplasm involving the cervix. "PGF and TNFAIP2 are important angiogenic factors, which were abnormal expression in cervical cancer (CC)." (PMID 33109108, 2020).
glioblastoma (2 papers, 2022 to 2024). The most malignant astrocytic tumor (WHO grade IV). "Both in vitro and in vivo experiments demonstrated that TNFAIP2 knockout increases surface expression of calreticulin (CALR), heat shock protein 70 (HSP70), and heat shock protein 90 (HSP90) in glioblastoma (GBM) cell lines, thereby inducing ICD." (PMID 39184045, 2024).
leukaemia (2 papers, 2024 to 2025). "The key findings demonstrated that enhanced expression of TNFAIP2 or the knockdown of miR-146b-3p significantly induced differentiation in MOLM-13 cells (a human leukemia cell line)." (PMID 40727567, 2025). "Although these studies have provided us with insight into the connection among differential expression of TNFAIP2, cell differentiation and the treatment of leukaemia, whether TNFAIP2 can directly induce leukaemic cell differentiation is not fully clarified, and the mechanism is still unclear." (PMID 38271140, 2024). "To prove whether TNFAIP2 can induce the differentiation of monocytic leukaemia cells, we transduced MOLM-13 cells with the TNFAIP2 overexpression (TNFAIP2-OE) construct and observed the expression of CD11b and CD14." (PMID 38271140, 2024).
melanoma (2 papers, 2016 to 2024). A malignant, usually aggressive tumor composed of atypical, neoplastic melanocytes. "The TNFAIP2 (TNF alpha-induced protein 2, Uniprot: Q03169) was identified in our study as a predictor of better therapy response and was also upregulated in melanoma patients in correlation with long survival both in proteomic and in PD1 and CTLA4 immunotherapy transcriptomic cohorts." (PMID 39015503, 2024).
sarcoma (2 papers, 2022 to 2024). A usually aggressive malignant neoplasm of the soft tissue or bone. "Except for those cancers [mesothelioma (MESO), SARC (sarcoma) and UVM] whose normal tissue data was unavailable or too few, significant differences in TNFAIP2 expression between tumor and normal tissue were found in 28 types of cancer." (PMID 36243694, 2022).
Shock (2 papers, 2018 to 2019). The state in which profound and widespread reduction of effective tissue perfusion leads first to reversible, and then if prolonged, to irreversible cellular injury. "Compared with the A allele, the G allele of TNFAIP2 rs8126 enhanced TNFAIP2 expression, decreased IL‐8 production, reduced the survival and increased organ dysfunction in patients experiencing septic shock." (PMID 30145807, 2018). "TNFAIP2, upregulated 33-fold, is phosphorylated upon LPS stimulation and its expression is linked to increased mortality in patients experiencing septic shock." (PMID 31191497, 2019).
atherosclerosis (1 paper, 2025). A disease characterized by the build-up of fatty material and calcium deposition in the arterial wall resulting in partial or complete occlusion of the arterial lumen. "In particular, Tnfaip2 deficiency has been shown to reduce inflammatory cytokine levels and plaque lesions in mouse models of atherosclerosis, indicating its pro-inflammatory role in disease progression." (PMID 40607379, 2025).
autoimmune disease (1 paper, 2020). A disorder resulting from loss of function or tissue destruction of an organ or multiple organs, arising from humoral or cellular immune responses of the individual to their own tissue constituents. "The association between autoimmune disease and TNFAIP2 variant rs1132339 is particularly noteworthy, as is the fact that TNFAIP6 variant rs1046668 appears to follow a recessive inheritance pattern." (PMID 32951330, 2020).
cardiac hypertrophy (1 paper, 2023). "We observed that Tnfaip2 can be downregulated by ISO treatment in both Tg and NTg mice, and its expression in Tg-Ufm1 mice treated with ISO was lower than that in NTg mice, indicating that Tnfaip2 is a UFMylation-associated gene in ISO-induced cardiac hypertrophy." (PMID 37980507, 2023). "We found 38 potential Ufm1-binding proteins and identified Tnfaip2 as a candidate UFMylation-associated gene in cardiac hypertrophy, which may provide novel evidence for further research on UFMylation in cardiac hypertrophy in vivo." (PMID 37980507, 2023). "In addition, the expression of Rpl26, a known substrate of UFMylation, was upregulated by ISO in NTg mice rather than in Tg-Ufm1 mice.These data indicated that Tnfaip2 may be a novel UFMylation-related gene that is associated with cardiac hypertrophy." (PMID 37980507, 2023). "However, Tnfaip2 has not been reported to be related to cardiac hypertrophy until recently." (PMID 37980507, 2023).
Chronic colitis (1 paper, 2021). A chronic inflammatory disease of the large intestine (colon, cecum and rectum). "By performing ChIP-PCR experiments, we found that the recruitment of p-STAT1 to the enhancers in the LCP2 and TNFAIP2 promoters was significantly increased in tissues of mice with chronic colitis compared to mice in the control group." (PMID 34112215, 2021). "In the current study, the binding of p-STAT1 to the enhancers of TNFAIP2 and LCP2 was significantly increased in tissues from mice with chronic colitis, suggesting that both p-STAT1 deposition and H3K27ac enrichment occur on the same enhancer of both the TNFAIP2 and LCP2 genes." (PMID 34112215, 2021).
colitis (1 paper, 2021). Inflammation of the colon. "We verified by ChIP-PCR that H3K27ac enrichment was increased at the enhancers of LCP2 and TNFAIP2 in mice with DSS-induced colitis." (PMID 34112215, 2021). "Furthermore, the mRNA expression of LCP2 and TNFAIP2 was upregulated in mice with DSS-induced colitis, and these changes were reversed after C646 administration." (PMID 34112215, 2021). "We found that p-STAT1 binds to EP300 to regulate the expression of LCP2 and TNFAIP2 by promoting H3K27 acetylation at enhancers, and thus, we further investigated whether the increase in H3K27ac levels mediated by EP300 is involved in the development of colitis in mice." (PMID 34112215, 2021).
diabetes (1 paper, 2025). "Studies showing exacerbated inflammatory responses and oxidative stress due to TNFAIP2 deletion align with our findings, reinforcing its potential role in diabetes and its complications." (PMID 40045538, 2025).
endometrial cancer (1 paper, 2018). Primary or metastatic malignant neoplasm involving the endometrium (mucous membrane that lines the endometrial cavity). "TNFAIP2 was induced by the RA agonist AM580 in endometrial cancer cells. qRT‐PCR verified that AM580 significantly induced TNFAIP2 expression." (PMID 30145807, 2018).
endothelial dysfunction (1 paper, 2025). In vascular diseases, endothelial dysfunction is a systemic pathological state of the endothelium (the inner lining of blood vessels) and can be broadly defined as an imbalance between vasodilating and vasoconstricting substances produced by (or acting on) the endothelium. "It was demonstrated that the genes associated with TNF-α signaling (TRAF1, TNFAIP2, and NFKBIZ) and oxidative stress regulation (SOD2) were significantly upregulated, suggesting that NS1 activates pathways critical for endothelial dysfunction and vascular inflammation." (PMID 40508120, 2025).
focal segmental glomerulosclerosis (1 paper, 2025). A renal disorder characterized by sclerotic lesions in the glomeruli. "Interestingly, podocytes, the glomerular visceral epithelial cells, also constitutively express TNFAIP2, and the TNFAIP2 knockout mice develop focal segmental glomerulosclerosis." (PMID 39939179, 2025).
head and neck cancer (1 paper, 2014). A primary or metastatic malignant neoplasm affecting the head and neck. "There is a TNFAIP2 3'-UTR rs8126 T>C genetic variant which has been proved to be associated with head and neck cancer susceptibility." (PMID 25383966, 2014).
non-small cell lung carcinoma (1 paper, 2023). A group of at least three distinct histological types of lung cancer, including non-small cell squamous cell carcinoma, adenocarcinoma, and large cell carcinoma. "More recently, TNFAIP2 upregulation was proven to be associated with cisplatin resistance in non-small cell lung cancer and urothelial cancer." (PMID 37525222, 2023). "In non-small cell lung cancer (NSCLC) and urothelial cancer, TNFAIP2 is significantly correlated with cisplatin resistance, but the underlying mechanism needs to be explored." (PMID 37525222, 2023).
pancreatic cancer (1 paper, 2017). "Testing additional patient‐derived pancreatic cancer cells reveals particular genes (ITGA1,TNFAIP2,COMMD7,RAB3D) that respond to APE1 knockdown similarly across all the cell lines." (PMID 28922540, 2017).
tuberculosis (1 paper, 2024). A chronic, recurrent infection caused by the bacterium Mycobacterium tuberculosis. "Additionally, the TNFAIP2-correlated genes were markedly enriched in pathways such as Tuberculosis, Osteoclast differentiation, Lysosome, Phagosome, and B-cell receptor signaling." (PMID 38271140, 2024).
uveal melanoma (1 paper, 2022). A melanoma derived from melanocytes of the uveal tract. "The lowest TNFAIP2 expression was observed in brain lower grade glioma (LGG), kidney chromophobe (KICH) and uveal melanoma (UVM), and intermediate expression was observed in AML." (PMID 36243694, 2022).
cancer (25 papers, 2013 to 2025). A tumor composed of atypical neoplastic, often pleomorphic cells that invade other tissues. "For instance, in a recent publication, there was a comparison of normal and tumor tissue for mRNA variants of TNFAIP2 among all the cancers in the TCGA database." (PMID 39015503, 2024). "Tnfaip2 has been reported to be associated with cancers and inflammation, which can be induced by tumor necrosis factor alpha (TNFα)." (PMID 37980507, 2023). "Upon basic evaluation of TNFAIP2 expression across different tumors, TNFAIP2 expression association with OS of cancer patients were studied." (PMID 36243694, 2022). "On the contrary, a high TNFAIP2 mRNA level is significantly associated with a long survival in several cancers, including bladder urothelial carcinoma, sarcoma and skin cutaneous melanoma." (PMID 30145807, 2018). "We genotyped four selected TNFAIP2 SNPs (rs8126 T>C, rs710100 G>A, rs1052912 G>A and rs1052823 G>T) and used the logistic regression analysis to assess associations of these SNPs with cancer risk." (PMID 23724109, 2013). "Dysregulation of TNFAIP2 was implicated in infectious diseases and cancers." (PMID 36243694, 2022). "Due to its significant functions in cell proliferation, angiogenesis, migration and invasion, TNFAIP2 could be a potential diagnostic biomarker and therapeutic target for cancer." (PMID 30145807, 2018). "A study on oesophageal squamous cell carcinoma (oeSCC) examined the TNFAIP2 3′-UTR rs8126 polymorphism, which was associated with increased cancer risk in Chinese populations." (PMID 41379397, 2025). "TNFAIP2 protein is known as an important player in inflammation, angiogenesis, proliferation, and migration and it is a cancer-related gene." (PMID 39015503, 2024). "In cancer treatment, TNFAIP2 was chosen as one of the six signature genes predicting chemotherapeutic and immunotherapeutic efficacies, with high-senescore patients benefiting from immunotherapy and low-senescore patients responsive to chemotherapy." (PMID 37787041, 2023). "By using Timer 2.0 database which mainly based on RNA sequencing data from TCGA cohort, TNFAIP2 expression was significantly correlated with OS of patients in nine cancer types." (PMID 36243694, 2022). "Due to the lack of knowledge of TNFAIP2 in leukemogenesis, we herein carried out an in-depth study on TNFAIP2 expression and its prognostic value in a range of cancers." (PMID 36243694, 2022). "Subsequently, TNFAIP2 expression levels between cancer and normal samples from 33 cancers were compared against each other in both TCGA and GTEx dataset." (PMID 36243694, 2022). "Taken together, these data suggested that the expression level and prognostic significance of TNFAIP2 was highly cancer-dependent, which needs to be further confirmed for the specific role of TNFAIP2 in each cancer." (PMID 36243694, 2022). "Then the genetic alteration status of TNFAIP2 gene in various types of cancer from TCGA cohorts was explored on cBioPortal web." (PMID 36243694, 2022). "On the other hand, prognostic value of TNFAIP2 expression in cancer patients has been reported rarely so far." (PMID 36243694, 2022). "TNFAIP2 has been reported to promote proliferation, angiogenesis, migration, and invasion of cancer." (PMID 36685901, 2022). "Alterations in TNFAIP2 are frequently coupled with human diseases, including cancers and infectious diseases." (PMID 34298942, 2021). "In different types of cancer, TNFAIP2 has been suggested to be an oncogene based on its positive role in cell proliferation, angiogenesis and migration." (PMID 30145807, 2018). "The expression of TNFAIP2 is frequently altered in human diseases, including cancers and infectious diseases." (PMID 30145807, 2018). "TNFAIP2 has potential as a biomarker for diagnosis and prognosis in a variety of cancers and infectious diseases." (PMID 30145807, 2018). "COMMD7, ITGA1, RAB3D, and TNFAIP2 have all been shown to be upregulated in various cancers including PDAC." (PMID 28922540, 2017).